NIPAL4 (NIPA like domain containing 4)
Description:
Acts as a Mg(2+) transporter. Can also transport other divalent cations such as Ba(2+), Sr(2+) and Fe(2+) but to a much less extent than Mg(2+) (By similarity). May be a receptor for ligands (trioxilins A3 and B3) from the hepoxilin pathway.
Synonyms: NIPA4; ICHYN; SLC57A6; ARCI6; ICHTHYIN
Tractability: Antibody: UniProt places it where antibodies can reach, with medium confidence; UniProt predicts a signal peptide or a membrane-spanning region; its Gene Ontology location is reachable by antibodies, with medium confidence.
Gene: Protein-coding gene on chromosome 5 (157,460,213 to 157,474,722, forward strand). Ensembl gene ENSG00000172548.
Subcellular location: Cell membrane
Pathways (Reactome):
Transport of small molecules: Miscellaneous transport and binding events
Gene Ontology:
Molecular function: protein binding; magnesium ion transmembrane transporter activity
Biological process: magnesium ion transport; magnesium ion transmembrane transport
Cellular component: membrane; plasma membrane
Genetic constraint (gnomAD): Loss-of-function variants: 18 observed, 25.74 expected, observed/expected ratio (o/e) 0.7, 90% interval 0.48 to 1.04. The upper end of that interval is the gene's LOEUF score, 1.04, which puts it in group 4 of 6, group 1 being the genes least tolerant of losing a copy. Missense variants: 399 observed, 464.21 expected, observed/expected ratio (o/e) 0.86, 90% interval 0.79 to 0.93. Synonymous variants: 152 observed, 189.46 expected, observed/expected ratio (o/e) 0.8, 90% interval 0.7 to 0.92.
Homologues: Orthologues: chimpanzee NIPAL4 (99% identical), macaque NIPAL4 (99% identical), rabbit NIPAL4 (93% identical), dog NIPAL4 (90% identical), pig NIPAL4 (89% identical), guinea pig NIPAL4 (87% identical), mouse Nipal4 (85% identical), rat Nipal4 (85% identical), tropical clawed frog nipal4 (60% identical), zebrafish nipal4 (55% identical), Caenorhabditis elegans nipa-1 (43% identical), Drosophila melanogaster spict (41% identical). Paralogues in human: NIPAL1 (53% identical), NIPA2 (52% identical), NIPA1 (30% identical), NIPAL2 (24% identical), NIPAL3 (21% identical).
Diseases named in the same sentence as NIPAL4 in open-access papers:
NIPAL4 is named in the same sentence as 24 diseases in open-access papers, as found by Europe PMC text mining. Sharing a sentence is not in itself a finding about the gene and the disease. The quoted sentences say what the papers report.
ichthyosis (15 papers, 2012 to 2026). Disorders of cornification that are characterized by visible scaling and/or hyperkeratosis of most or all of the skin. "The causative gene for congenital ichthyosis, NIPAL4, encodes a Mg2+ transporter and is involved in increases in intracellular Mg2+ concentrations that depend on keratinocyte differentiation." (PMID 38692573, 2024). "NIPAL4 has been identified as the causative gene of autosomal recessive congenital ichthyosis, and 34 autosomal recessive congenital ichthyosis-causing mutations have been reported to date." (PMID 38692573, 2024). "Gene expression profiling of skin from patients with congenital ichthyosis identified significant upregulation of psoriasis hallmark genes, while Nipal4-knockout mice exhibited neonatal lethality due to skin barrier defects." (PMID 37277347, 2023). "Loss-of-function mutations in NIPAL4 (NIPA like domain containing 4) cause autosomal recessive congenital ichthyosis." (PMID 32054030, 2020). "Mutations in NIPAL4 genes are described in patients with congenital ichthyosis, a monogenic disease with cutaneous manifestation but unknown underlying pathogenetic mechanisms." (PMID 37277347, 2023). "Exome sequencing followed by segregation analysis identified pathogenic variants in four established ichthyosis-associated genes: CYP4F22, FLG, ALOX12B, and NIPAL4." (PMID 42196615, 2026). "To date, multiple genes have been shown to be associated with ichthyosis, including ALOXE3, ALOX12B, TGM1, CYP4F22, NIPAL4, and ABCA12." (PMID 24278723, 2012). "In the American Bulldog, mutations in the NIPAL4 gene are related to non-epidermolytic ichthyosis and in humans to autosomal recessive congenital ichthyosis." (PMID 36006348, 2022). "Other dog models for human non-syndromic ichthyoses include Norfolk Terriers with an epidermolytic ichthyosis caused by a KRT10 variant, Bulldogs with ARCI caused by a NIPAL4 variant, and Jack Russell Terriers with another form of ARCI caused by a TGM1 variant." (PMID 28249031, 2017). "There are 6 genes currently known to be associated with ichthyosis: ALOXE3, ALOX12B, TGM1, CYP4F22, NIPAL4, and ABCA12, and although thought to be unrelated, both the probands from family 1 and family 2 harboured an identical novel missense variant, c.G4676T, p.Gly1559Val in ABCA12." (PMID 24278723, 2012). "Therefore, animals with deficient NIPAL4 protein fail to form normal lamellar bilayers, leading to the appearance of the typical clinical signs of non-epidermolytic ichthyosis." (PMID 36006348, 2022). "Most well documented forms of canine ichthyosis are non-epidermolytic, involving genetic variants in ABHD5 or PNPLA1 in golden retrievers, TGM1 in Jack Russell terriers, NIPAL4 in American bulldogs, and ASPRV1 in a German shepherd dog." (PMID 36251712, 2022). "Humans with NIPAL4 deficient ARCI may be characterized phenotypically as non-bulbous congenital ichthyosiform erythroderma (CIE; fine white scale with erythema) or lamellar ichthyosis (LI; thick brown scale) as is typical for nonepidermolytic ARCI regardless of the genetic variant." (PMID 28122049, 2017).
autosomal recessive congenital ichthyosis (10 papers, 2012 to 2024). Autosomal recessive form of inherited ichthyosis. "To date, only a limited number of mutations in the NIPAL4 gene have been described to be correlated with autosomal recessive congenital ichthyosis (ARCI)." (PMID 35757399, 2022). "Eight patients were affected by autosomal recessive congenital ichthyosis associated with ALOX12B, NIPAL4, and TGM1 mutations." (PMID 38791074, 2024). "Exome sequencing reveals a novel homozygous likely pathogenic variant in NIPAL4 gene, that might underlines the EKV-like Autosomal Recessive Congenital Ichthyosis (ARCI) phenotype in this family." (PMID 34669720, 2021).
congenital ichthyosis (6 papers, 2014 to 2024). "In the group of ARCI, NIPAL4 mutation is associated with a pronounced keratoderma, while ALOXE3 mutation is associated with an ichthyosis vulgaris-like pattern." (PMID 26762237, 2016).
Palmoplantar keratoderma (3 papers, 2016 to 2022). Abnormal thickening of the skin of the palms of the hands and the soles of the feet. "Our findings showed that palmoplantar keratoderma was associated with NIPAL4, TGM1, CYP4F22 mutations and CERS3 deletion, but with varying severity." (PMID 34983512, 2022). "Yellowish severe keratoderma was found to be associated with NIPAL4 variations and brachydactyly to TGM1 mutations." (PMID 34983512, 2022). "In this study, the clinical features of the proband present partial similarity to those of the phenotype associated with NIPAL4 mutations including fine, brown scaling with variable erythroderma and mild palmoplantar keratoderma." (PMID 34669720, 2021). "Thus, yellowish keratoderma could be indicative of NIPAL4 mutation in ARCI patients." (PMID 34983512, 2022).
Hyperkeratosis (2 papers, 2017 to 2021). Hyperkeratosis is a histopathological term defining a thickened stratum corneum and may be present in many different skin conditions, with many possible overlaps. "A feature of NIPAL4 deficient ARCI in humans is yellow palmar plantar keratoderma, and interestingly, the ABDs also develop paw pad hyperkeratosis with yellow discoloration, but it is not observed until over one year of age (EAM, unpublished observation)." (PMID 28122049, 2017).
psoriasis (2 papers, 2023 to 2024). An autoimmune condition characterized by red, well-delineated plaques with silvery scales that are usually on the extensor surfaces and scalp. "The strongest reQTL that was linked to an association study was in LD with a risk variant for psoriasis and influenced NIPAL4 expression." (PMID 37277347, 2023). "Unfortunately, we could not test for colocalization for NIPAL4 and psoriasis, because no GWAS summary statistic was publicly available for this trait, which showed association for the corresponding locus." (PMID 37277347, 2023).
hypohidrosis (1 paper, 2021). diminished sweating in response to appropriate stimuli. "However, they differ by the absence hypohidrosis or ectropion and the absence of generalized skin scaling that are major manifestations in patients with ARCI harboring NIPAL4 mutations." (PMID 34669720, 2021).
lamellar ichthyosis (1 paper, 2021). A keratinization disorder characterized by the presence of large scales all over the body without significant erythroderma. "Loss of function mutations of NIPA like domain containing 4 (Nipal4), a putative Mg2+ transporter, have been shown to be causative for lamellar ichthyosis." (PMID 33652877, 2021).
MODY (1 paper, 2023). "Similarly, in the case of MODY diabetes, the heterozygous MLKL loss-of-function mutation also segregated with heterozygous deleterious mutations in the known MODY gene PDX1, as well as ERN2, NIPAL4 and SPTBN4 in affected individuals." (PMID 36755069, 2023).
Palmoplantar hyperkeratosis (1 paper, 2019). Abnormal thickening of the skin localized to the palm of the hand and the sole of the foot. "Furthermore, all Saudi Arabian patients showed palmar hyperlinearity but only TGM1 and ABCA12 affected individuals presented palmoplantar hyperkeratosis, while NIPAL4 and CYP4F22 presented only plantar keratosis." (PMID 30600594, 2019).
cardiac disease (1 paper, 2024). "Regarding the miRNA–mRNA pairs, miR-125a-5p/NIPAL4, miR-135a-5p/ZNF385B, miR-140-3p/FKBP3, miR-140-3p/SKP1 and miR-140-3p/NDUFA4, very little or nothing is known about the function of these genes in cardiac disease." (PMID 39200271, 2024).
tumor (1 paper, 2022). "Our work demonstrated that HTR3A and NIPAL4 expression were associated with prognosis and tumor-infiltrating immune cells." (PMID 35757399, 2022). "Our study contributes novel insights into the interactions between tumor cells and infiltrating immune cells, confirming that HTR3A and NIPAL4 may be involved in BRAF-mutated PTC by interfering with immune cells." (PMID 35757399, 2022).
NIPAL4 also shares sentences with these, for which no sentence is quoted: ichthyosiform erythroderma (2 papers); age-related macular degeneration (1); brachydactyly (1); cone-rod dystrophy 2 (1); congenital ichthyosiform erythroderma (1); Erythema (1); erythroderma (1); erythrokeratodermia variabilis (1); ichthyosis vulgaris (1); Myokymia (1); pustular psoriasis (1); spinocerebellar ataxia (1).